SOX9 (SRY-box transcription factor 9)
Diseases named in the same sentence as SOX9 in open-access papers (continued):
Sharing a sentence is not in itself a finding about the gene and the disease.
cancer (continued). "Previous studies showed that high expression levels of PDGFC, SOX9, BCL11A, and DIO2 were associated with poor response to chemotherapy in cancer cells and short survival time of various patients, which could be regarded as negative prognostic factors." (PMID 36092919, 2022). "SOX9 could be an emerging target for anticancer drugs and a prognostic biomarker for cancer drug resistance." (PMID 36003340, 2022). "We then subset and clustered the epithelial lineage cells and identified the normal acinar (Amy1+ and Amy2a2+) and islet/ductal cells (Pyy+ and Sst+, Ins1+ and Ins2+) as well as a cancer cell cluster with normal epithelial lineage marker expression excluded (Sox9+ and Krt18+)." (PMID 35941362, 2022). "Furthermore, the inhibition of SOX9 or DIO2 has been reported to be a potential therapeutic strategy for cancer." (PMID 36092919, 2022). "Herein, we made efforts in examining the hypothesized regulatory effects of OTUD1 on the NSCLC cell growth dynamics and chemoresistance, and clarifying the potential anti-cancer network of OTUD1/YAP1/SOX9/SPP1." (PMID 36182943, 2022). "SOX9 participates in the progression of many cancers through this model." (PMID 35700516, 2022). "Interactions between lncRNAs and SOX9 have been explored in the context of cancers." (PMID 36114905, 2022). "Next, we determined the effect of SOX9 silencing in cancer cell proliferation." (PMID 35159173, 2022). "SOX9 overexpression has been found to play a critical role in various cancers." (PMID 36230806, 2022). "SOX9-positive cells have characteristics of cancer stem cell." (PMID 35221802, 2022). "However, a strong correlation between the level of SOX9 protein expression and the level of the cytoplasmic cancer stem cell marker ALDH1 expression was found only in the lymph node metastatic HGOC group." (PMID 35159173, 2022). "In addition, the gut microbiota plays a critical role in the regulation of cancer metastasis through the IL11/circular RNA/miRNA/SOX9 axis." (PMID 36110534, 2022). "SOX9 has been shown to influence cancer progression through Wnt signaling." (PMID 35563098, 2022). "Similarly, Sox9 siRNA has been previously shown to be efficient in the knock-down of Sox9 in cancer and other pathologies." (PMID 33963183, 2021). "In HCC, reportedly, miR-1-3p represses the proliferation of cancer cells through targeting SOX9." (PMID 34395415, 2021). "Studies had shown that miRNA-216b can inhibit the proliferation and invasion of NSCLC cells by directly targeting the 3′ untranslated region and negatively regulating the expression of SOX9, which was an oncogene regulated by multiple miRNAs in various types of human cancer." (PMID 34470640, 2021). "Moreover, THY1 expression was positively related to the level of SOX9, a classical biomarker of cancer stemness." (PMID 35071018, 2021). "Consistent with this, increased expression of markers associated with poor differentiation and increased epithelial–mesenchymal transition and cancer metastasis in cSCC was observed in cSCC tumors of FliiTg/Tg mice, including increased talin, K14 and cytoplasmic SOX9." (PMID 34948000, 2021). "Like other cancer cells, Sox9 and SLUG enhance the metastatic propensity of NSCLC cells." (PMID 34445544, 2021). "GSEA results also showed that patients with high SOX9 expression had enrichment for the TGF-β signaling pathway and pathway in cancer, while the low SOX9 expression group had enrichment for the primary immunodeficiency pathway and the T cell receptor signaling pathway." (PMID 34778027, 2021). "Correlation between expression of SOX9 and poor patient prognosis strongly suggests that SOX9 might have an oncogenic role in several types of cancer, which remains to be explained in further studies." (PMID 34442467, 2021). "Studies have confirmed that SOX9-overexpressing cancer cells are resistant to oxaliplatin." (PMID 34124145, 2021).
cancer (continued). "Considering the characteristics of cancer stem cells, we explored whether SOX9 participates in anticancer drug resistance by affecting DNA damage repair in cancer cells." (PMID 34124145, 2021). "Patients in PD group had the highest expression of THY1 and SOX9, a marker of cancer stemness." (PMID 35071018, 2021). "Taken together, the ceRNA network regulates the expression of SOX9 and plays an important role in ovarian carcinogenesis, development, maintenance of cancer stem cell properties, anti-apoptosis, migration, and invasion of cancer cells." (PMID 34881182, 2021). "The up‐regulation of SOX2, SOX4, SOX5, SOX8, SOX9 and SOX18 are found to be associated with poor outcome in different cancer types; however, the up‐regulation of SOX11 and SOX30 is favourable for the prognosis in other cancer types." (PMID 32363730, 2020). "Moreover, in cancer cells, SOX9 inhibits apoptosis and promotes proliferation, invasion, and metastasis." (PMID 32317630, 2020). "Moreover, SOX9 has emerged as an essential regulator of cancer cell stemness, differentiation, and apoptosis." (PMID 32317630, 2020). "Thus, the functions of p62 and SOX9 in normal cell homeostasis and development provide cancer cells with a growth advantage and promote tumorigenicity." (PMID 31959131, 2020). "However, further studies should be performed to confirm the suggested potential role of Sox9 and Lgr6, both at the protein and mRNA level, as cancer markers of malignancy." (PMID 32397255, 2020). "Furthermore, analysis of gut microbiota by deep sequencing combined with animal models and fecal transplantation identified a critical role of gut microbiota in the regulation of cancer progression and metastasis through IL-11/circRNA/miRNA/SOX9 axis." (PMID 32686598, 2020). "In order to evaluate the role of SOX9 in cancer cell survival, we studied apoptosis." (PMID 31941916, 2020). "This was most obvious at a concentration of 50 μM, indicating that the potential of SOX9 to change the sensitivity for this cancer drug, depending on its expression levels, could be useful in a personalized treatment strategy." (PMID 33076370, 2020). "In line with this, previous studies analyzed the correlation between SOX9, BMI1 and p21CIP in different types of cancers and showed independently that SOX9 regulates proliferation through a positive correlation with BMI1 and an inverse correlation with p21CIP expression." (PMID 31941916, 2020). "Given the prevalence and critical role of SOX9 in cancer progression, it is crucial to understand how SOX9 protein stability is regulated and whether the dysregulation of SOX9 protein abundance contributes to cellular resistance to therapy." (PMID 33173725, 2020). "SOX9 has proven its functional role in various aspects of cancer biology." (PMID 31057614, 2019). "SOX9 deletion prevents tumorigenesis in prostatic and pancreatic mouse cancer models." (PMID 29416606, 2018). "SOX9 was recently announced as a novel cancer stem cell marker." (PMID 29614966, 2018). "TWIST, SLUG and SOX9 have lately been described as cancer stems cell markers inducing EMT." (PMID 29739401, 2018). "The defensive effects of SOX9 for CCA cells are not limited to cancer cells facing chemotherapy." (PMID 30420613, 2018). "Sex-determining region Y (SRY)-box9 protein (SOX9) is a transcription factor that controls cell fate decision during the development and homeostasis of a broad range of tissues, and is expressed in a wide range of cancers." (PMID 29416606, 2018). "Therefore, we analyzed the relationship between the co-expression of PHGDH and Oct4 or SOX9, and the clinical outcome from cancer." (PMID 30250195, 2018). "However, the current results do suggest that SOX9 plays a role in the maintenance of cancer stem cell phenotypes." (PMID 30420613, 2018).
cancer (continued). "In this study, we herein issued a comprehensive meta-analysis to appraise the prognostic significance of SOX9 overexpression in solid human tumors, and illustrate the clinical value of SOX9 as a prognostic indicator and potential therapeutic target for malignant tumor patients." (PMID 29348895, 2017). "Genes associated with the most common VELs included novel genes and several known oncogenes and tumour suppressors implicated in CRC as well as other forms of cancer, including MYC10, 16, BMP4 (refs 17, 18), PHLDA1 (refs 19, 20, 21, 22), SOX9 (refs 23, 24, 25) and TRIB3 (refs 26, 27)." (PMID 28169291, 2017). "SOX9 prevailed a poor prognostic factor in all cancer validation cohorts (p<0.05)." (PMID 29121666, 2017). "The observation that linc-ROR and SOX9 are coordinately expressed in ESCC tissues led to the hypothesis that linc-ROR might promote stem cell-like properties and cancer progression through the regulation of pluripotency transcription factor SOX9." (PMID 29237490, 2017). "In several cancers, miR-101 inhibits SOX9 by direct targeting to suppress cancer cell proliferation, migration and invasion, suggesting that there might be RISC complex in both miR-101 and SOX9." (PMID 29212230, 2017). "Given that CSCs may be involved in cancer initiation steps, we suggest that SOX9 may be used as an early biomarker for SWCNT-induced carcinogenesis." (PMID 28912540, 2017). "ii) SOX9 is important in maintaining the properties of cancer stem cell (CSC) in various tumors." (PMID 29348895, 2017). "Importantly, such resistance to inflammation-associated colon tumorigenesis in Mx1-Cre;Gankyrinf/f mice was associated with a significant reduction of pro-inflammatory responses (IL-17 and TNF-α) and expression of cancer stem cell markers (Bmi1 and Sox9)." (PMID 28160571, 2017). "SOX9, a member of the SOX (SRY-related HMG box) family, is a transcription factor that is required for prostate organogenesis, and its dysregulation has been implicated in cancer pathogenesis." (PMID 28465491, 2017). "What remains to be a question is the regulatory mechanism of Sox9 expression in this cancer." (PMID 27105493, 2016). "SOX9 was also studied in the cancer context of numerous tissues including the colon." (PMID 27429045, 2016). "MiR-206 plays an important anti-cancer role via targeting c-Met, Bcl2, cyclinD1, and Sox9 in NSCLC." (PMID 27806334, 2016). "One recent study has also demonstrated that SOX9, which was highly expressed around the bottom of the crypts and regulated cancer stemness, inhibited differentiation of CRC cells and carcinoembryonic antigen gene, suggesting that CEA expression was downregulated in CSCs." (PMID 27813496, 2016). "SOX9 participates in the cancer stem cell state and maintains mesenchymal features in some cancers." (PMID 27683122, 2016). "Further dissection of the epigenetic regulation of Sox9 expression in this cancer may also provide insights on the therapeutic perspective." (PMID 27105493, 2016). "Collectively, these studies indicate that SOX9 functions as an oncogene and might represent an anti-cancer target." (PMID 26384302, 2015). "Recent studies have demonstrated that Sox9 is required for the oncogenesis of several cancer types." (PMID 25955804, 2015). "Such a cooperative role fits well to our observation that SOX9 expression was linked to PTEN deletion at least in the subset of cancers lacking ERG fusion." (PMID 26030748, 2015). "However, for PTEN, the separate analysis of ERG-positive and ERG-negative cancers revealed a striking bimodal relationship with SOX9 expression." (PMID 26030748, 2015). "Aberrant expression of SOX9 in various cancers suggests a role of SOX9 in these diseases." (PMID 26040697, 2015). "Sox9 has gained increasing importance both functionally and as a prognostic factor in cancer." (PMID 25004243, 2014).
cancer (continued). "SOX9 broadly plays a role in cancerogenesis and is overexpressed in many types of human cancers, where SOX9 exhibits pro-oncogenic properties of promoting cell proliferation, inhibiting cell senescence, and collaborating with other oncogenes in neoplastic transformation." (PMID 24828201, 2014). "SOX2 and SOX9 both exhibited frequent over- and underexpression within the same cancer type, potentially indicating their dual roles in cancer and that they could be differentially selected for in cells with different genetic backgrounds." (PMID 25594027, 2014). "In particular, recent studies have indicated the emerging role of SOX9 in various human cancers." (PMID 24188461, 2013). "All these findings suggest that SOX9 may play important roles in cancer development and progression, which prompted the authors to ask whether it is also clinically associated with the progression of NSCLC." (PMID 22385677, 2012). "For instance, Sox9 plays broadly roles in cancerogenesis and is overexpressed in many types of human cancers, where Sox9 exhibits pro-oncogenic properties of promoting cell proliferation, inhibiting cell senescence, and collaborating with other oncogenes in neoplastic transformation." (PMID 23443092, 2012). "Such a hypothesis may explain the necessity for Sox9 in cancer formation and its dispensability in normal tissue maintenance." (PMID 22761195, 2012). "Once the functional consequences of SOX9 CpG island hypermethylation were determined in vitro, it was tested whether hypermethylation of this gene was cancer-specific." (PMID 18087279, 2008). "Prior work revealed that Semaphorin-7a (SEMA7A) also promotes cancer stem cell and pro-survival phenotypes in luminal progenitor cells during involution, and we observe a population of luminal progenitor cells that co-expresses Sox9 and Sema7a during involution." (PMID 42239249, 2026). "Our observations suggest that SOX9-expression, in addition to hormone measurements, may serve as an indicator to estimate additional aspects of testicular tissue samples from childhood cancer patients." (PMID 39188568, 2024). "Recent studies have reported the participation of SOX9 in the regulation of stem cells, cell plasticity and the epithelial-mesenchymal transition, which promotes the activation of several signaling pathways leading to cancer development, cancer progression, and drug resistance." (PMID 38956258, 2024). "Furthermore, high expression of SOX9 has been described as a feature of cancer stem-like cells." (PMID 35779228, 2023). "It is logical to speculate that SOX9 may promote cancer through activating RAP1." (PMID 37919693, 2023). "According to the circRNA target profiling and pathway enrichment analysis, the high‐confidence DECs could influence the expression of cancer stem cell‐associated core signature genes such as ALDH1A3, SOX9, CD109, LIF and BMPR1 via negative regulation of miRNAs." (PMID 35579852, 2022). "SOX9 elevation could act with WNT signaling to drive cancer progression." (PMID 36123852, 2022). "LINC-ROR stimulates cancer stem cell phenotype and ESCC progression through the deregulation of SOX9, as a TF involved in embryogenesis and maintenance of stem/progenitor cells, to coordinately promote cell proliferation, motility, self-renewal capacity, and cancer stemness state." (PMID 33745265, 2021). "However, key SOX9 regulatory genes in most human tissues and cancers have yet to be established; it maybe that they are cell type and developmental stage specific." (PMID 34881182, 2021). "In addition, SOX9 levels were significantly lower in the normal cells surrounding the cancer tissues in the CC + GL group, which suggests that GL may affect stemness by attenuating inflammation." (PMID 33807620, 2021). "Thus, SOX9 is required for cancer cell survival, wherein exerts an antiapoptotic role." (PMID 31941916, 2020). "It was previously shown in HCC cancer stem cells that Opn may be controlled by Sox9." (PMID 30778201, 2019).
cancer (continued). "Moreover, SOX9 is clinically relevant as it may contribute in diagnosis, prognosis, and therapeutic among diverse types of cancer." (PMID 31057614, 2019). "Furthermore, SOX9 is a universal prognosis marker across several types of cancer." (PMID 29121666, 2017). "Therefore, taken together, the elevated SNAI2 and SOX9 protein levels may also have greatly contributed to the up-regulation of cancer stem cell features and motility of those DU145FP cells." (PMID 28698547, 2017). "Additionally, SOX9 is significantly enriched in a sphere model system for cancer stemness." (PMID 29121666, 2017). "These two situations are, however, slightly different: firstly, intestinal cells of knocked out mice are not malignant tissue unlike cancer cells that exhibit a number of mutated genes; secondly SOX9 is completely absent from knocked out mice, whereas siRNA only induce a partial SOX9 knock down." (PMID 27429045, 2016). "In addition, Sox9 is defined as a specific cancer stemness biomarker." (PMID 27556703, 2016). "However, further investigation is needed to clarify whether Sox9 indeed modulates the expression of Bbf2h7 in cancer cells." (PMID 25955804, 2015). "Whether SOX9 may be involved in NF-Y target gene regulation in normal intestinal mucosal cells or whether the interaction of SOX9 and NF-Y is entirely specific to the context of cancer should be also addressed in a future study." (PMID 26040697, 2015). "Therefore, it is possible that Sox9 may be involved in the proliferation of cancer cells through induction of Bbf2h7 expression." (PMID 25955804, 2015). "However, it was unclear if S100P is necessary for the functions of SOX9 in cancer progression." (PMID 26009899, 2015). "We were also interested in the effect of autophagic inhibition on reported virulent transformation markers, such as CXCR4, SOX9, and CD44, and on chemokines, such as CXCL1 and IL8, since various reports have indicated that these markers and inflammation are associated with cancer initiation." (PMID 26496833, 2015). "It was then necessary to test whether SOX9 methylation was a cancer-specific epigenetic event." (PMID 18087279, 2008). "Compared with ESCs, CSBPs are characterized by lower and narrower H3K27me3 deposition alongside abundant H3K4me3, thus permitting the persistent expression of genes critical for cancer stem cell (CSC) formation and maintenance, as exemplified by SOX9." (PMID 41414814, 2025). "HK2 also regulates stemness properties of cancer cells by upregulating key stemness genes such as NANOG, SRY-Box 9 (SOX9), CD117, octamer-binding transcription factor 4 (OCT4), and Krüppel-like factor 4 (KLF4)." (PMID 40427188, 2025). "Consistent with the previously noted impact of miRNA-21 on stemness and survival in other cancers, we observed that silencing miRNA-21 led to a significant downregulation of key stemness markers OCT4, SOX9, and NANOG." (PMID 39851519, 2025). "Conversely, in other cancers, EGR1 can enhance stemness and predict poor outcomes in uterine cervical cancer by promoting SOX9 expression." (PMID 39866235, 2025). "Based on the notion of “transcriptional addiction,” targeting transcription regulators, including CDK7, has emerged as a powerful strategy to attenuate cancer dependency, particularly in cancers that rely on SE-driven genes (e.g., MYC, RUNX2, SOX2, SOX9)." (PMID 39800748, 2025). "Antisense transcripts of TF genes such as SOX9 and WT1 have been shown to have functional roles in cancer." (PMID 41255714, 2025). "The role of SOX transcription factors and the effect of their dysregulation on cancer progression and on therapy response is not fully understood and some data investigating the impact of SOX2 and SOX9 in OSCC remain controversial." (PMID 39180200, 2025). "Recently, SOX9 has emerged as a promising therapeutic target, as evidenced by its identification through CRISPR-Cas9 screens of human cancers." (PMID 40240356, 2025).